FGFR4 (fibroblast growth factor receptor 4)
Diseases named in the same sentence as FGFR4 in open-access papers (continued):
Sharing a sentence is not in itself a finding about the gene and the disease.
colorectal cancer (continued). "Our work now reports that FGFR4 enhanced the response of human colorectal cancer cells to radiation therapy by upregulating RAD51 and consequently increasing HR capacity." (PMID 27650548, 2016). "Here, we investigated for the first time the role of FGFR4 in the resistance of colorectal cancer cells to radiotherapy, and the possible mechanisms of interaction with the DNA damage response machinery (DDR)." (PMID 27650548, 2016). "Decrease in the tumorigenic and invasive capacity of colorectal cancer cells by FGFR4 silencing was accompanied by a decrease of the expression of Snail and Twist and an increase of E-cadherin expression." (PMID 26498355, 2016). "Mechanistic study shows tumor-associated fibroblasts (TAF) -derived FGF19 is required for TAF-induced FGFR4/Wnt activation and governs colorectal cancer cell metastasis in vivo." (PMID 26498355, 2016). "FGFR4 expression levels are very restricted in adult tissues, except in several solid tumors including colorectal cancer, which showed overexpression of FGFR4." (PMID 23696849, 2013). "Previously, our group identified FGFR4 as an autoantibody target in colorectal cancer (CRC) using protein microarrays." (PMID 23696849, 2013). "Collectively, these data support an important role of FGFR4 in tumorigenesis and invasion of colorectal cancer, being more relevant for metastatic SW48 cells." (PMID 23696849, 2013). "Our results suggest that FGFR4 overexpression appears to be a major determinant to influence tumorigenesis and progression in colorectal cancer." (PMID 23696849, 2013). "Collectively, targeting of FGFR4 with different strategies showed a great potential of this receptor as therapeutic target in colorectal cancer and a potential effect on angiogenesis." (PMID 23696849, 2013). "Collectively, these data using three different colorectal cancer cell lines confirm that FGFR4 is an important effector in EMT." (PMID 23696849, 2013). "The results obtained with different approaches for FGFR4 blocking indicate the efficacy of FGFR4-targeting as therapeutic alternative for colorectal cancer." (PMID 23696849, 2013). "Collectively, our data support a crucial role for FGFR4 in tumorigenesis, invasion and survival in colorectal cancer." (PMID 23696849, 2013). "In total, we found 3 SNPs in the FGFR4 cDNA in 4 colorectal cancer cell lines and 20 cancer samples." (PMID 23696849, 2013). "Thus, FGF19/ELF4/FGFR4 generates a positive feedback loop to enhance colorectal cancer cell metastasis." (PMID 40083328, 2025). "Furthermore, Transwell assays demonstrated that the invasive ability of FGFR4-knockdown cells was also markedly lower than that of the control group, indicating that FGFR4 knockdown inhibits the invasiveness of colorectal cancer cells." (PMID 41210688, 2025). "Based on our previously published data on the prognostic role of FGFR4 in colorectal cancer and data on FGFR4 expression on esophageal squamous cell carcinoma, one would anticipate finding alike results in patients with adenocarcinomas of the esophago-gastric junction." (PMID 31527546, 2019). "However, the results obtained are in agreement with qualitative FGFR4 expression described in breast and colorectal cancer cells." (PMID 28376106, 2017). "Colorectal cancer cell lines cocultured with tumor-associated fibroblasts (TAF) induced significant overexpression of FGFR4, but not of other FGFRs." (PMID 28056982, 2017). "Also, fibroblast growth factor receptor 4 (FGFR4) has been indicated to be an inducer of chemoresistance in colorectal cancer through regulation of FLIP expression." (PMID 27057637, 2016). "We followed two different strategies to prove the therapeutic value of FGFR4 in colorectal cancer." (PMID 23696849, 2013). "In summary, suppression of FGFR4 expression in colorectal cancer cells produced a reversion of the mesenchymal to a more epithelial phenotype and the reduction of tumorigenic properties of colorectal cancer cells." (PMID 23696849, 2013).
colorectal cancer (continued). "This FGFR4 effect on cell apoptosis in response to oxidative stress may play a role in advanced colorectal cancer, facilitating the survival of metastatic colorectal cancer cells." (PMID 23696849, 2013). "In addition, we define a new role for FGFR4 as regulator of the epithelial-mesenchymal transition and invasion in colorectal cancer that makes it an attractive target for therapeutic intervention." (PMID 23696849, 2013). "However, FGFR4 was recently suggested as a potential mediator of drug resistance in colorectal cancers, and signaling through FGFR might still be significant even in other types of gastrointestinal cancers." (PMID 29573334, 2018). "Thus we define a new role for FGFR4 as regulator of radiation-induced DSB repair in colorectal cancer, making it a candidate predictive marker that identifies those patients who may best profit from neoadjuvant chemoradiation." (PMID 27650548, 2016). "Furthermore, FGFR4 has also been shown to play a crucial role in tumorigenesis, invasion, and survival in colorectal cancer, and its specific targeting marks a new avenue of colorectal cancer therapy." (PMID 25852822, 2015). "In addition, FGFR4 targeting demonstrated its applicability for colorectal cancer therapy." (PMID 23696849, 2013). "Recent research shows FGF19 induces ELF4 in colorectal cancer, driving metastasis via ELF4‐mediated FGFR4 and Src kinase signaling." (PMID 41287970, 2025). "To investigate the role of FGFR4 in the progression of colorectal cancer, we conducted transcriptomic sequencing analysis using the FGFR4-stably silenced SW480 colorectal cancer cell line." (PMID 41210688, 2025). "The expression of FGFR4 is also regulated by forkhead box C1 (FOXC1), which directly targets FGFR4, promotes its transcription, and drives metastasis of colorectal cancer cells." (PMID 37750089, 2023). "In colorectal carcinoma (CRC), TRIP13 interacted with the receptor tyrosine kinase fibroblast growth factor receptor 4 (FGFR4) and activated the epidermal growth factor receptor (EGFR)/AKT pathway to induce EMT." (PMID 36268276, 2022). "FOXC1 is overexpressed and promotes colorectal cancer metastasis by activating the expression of ITGA7 and FGFR4." (PMID 34957298, 2021). "In colorectal cancer (CRC), fibroblast growth factor receptor 4 (FGFR4) is upregulated and acts as an oncogene." (PMID 27650548, 2016). "To confirm FGFR4 specificity, we used commercial anti-FGFR4 antibodies on SW480 and SW48 colorectal cancer cells." (PMID 23696849, 2013). "A recent study showed that FGF-1/-3/FGFR4 signaling in CAF promotes tumor progression in colon cancer through ERK and MMP-7, inducing angiogenesis and cell proliferation, which suggests a crucial role of CAF and FGF signaling in colorectal cancer." (PMID 33946534, 2021). "To study the role of FGFR4 overexpression in tumorigenesis and metastasis, we studied the effect of FGFR4 expression in SW48, SW480 and SW620 colorectal cancer cell lines, which did not contain the Arg388 polymorphism." (PMID 23696849, 2013). "In colorectal cancer, overexpression of ELF4 transactivates fibroblast growth factor receptor 4 (FGFR4) and non-receptor tyrosine kinase (SRC) to facilitate the metastasis of colorectal cancer." (PMID 40083328, 2025). "Without treatment, scrambled and FGFR4-silenced SW480 and SW48 colorectal cancer cells showed similar levels of apoptosis." (PMID 23696849, 2013).
lung carcinoma (32 papers, 2007 to 2026). "The intestinal cancer exhibited the same rare mutations observed in the lung cancer tissue, including FGFR4 p.G388R, suggesting a metastatic origin of the intestinal tumor from the lung." (PMID 38650006, 2024). "The most common FGFR4 genetic variant in lung cancer is the SNP rs351855 G/A, which is in the exon 9 coding region of the FGFR4 gene." (PMID 32781755, 2020). "In this work, we aimed to study the effect of the FGFR4-388Arg variant on lung cancer oncogenic behavior, its relationship with EMT in this setting, and its impact on patient prognosis." (PMID 29402970, 2018). "The FGFR4-388Arg variant has been related to poor prognosis in several types of cancer, including lung cancer." (PMID 29402970, 2018). "In some retrospective studies of lung cancer cohorts analyzing each histological subtype independently, the FGFR4-388Arg variant was linked to lymph node involvement and poorer overall survival (OS) in ADC patients." (PMID 29402970, 2018). "In this work, we report the pro-oncogenic role of the FGFR4-388Arg variant in lung cancer; this variant correlates with greater STAT3 and MAPK activation and higher expression of EMT markers in vitro." (PMID 29402970, 2018). "In previous retrospective studies, the association of the FGFR4-388Arg genotype to prognosis in lung cancer patients has remained controversial." (PMID 29402970, 2018). "In summary, we have shown here that the FGFR4-388Arg variant has an impact on the tumorigenic behavior of lung cancer cell lines by inducing an EMT expression profile through increased N-cadherin expression and overactivation of MAPK and AKT signaling." (PMID 29402970, 2018). "In terms of cancer type, the FGFR4 rs351855 G>A polymorphism was found to modify susceptibility to breast, prostate, and lung cancer." (PMID 28445975, 2017). "Similar association between FGFR1, FGFR3, FGFR4 and brachyury gene expression was also observed in lung cancer cell lines." (PMID 27893433, 2016). "Targeted genetic dependency screen is an efficient approach to identify somatic cancer alterations and was used to identify gain-of-function (GOF) mutations in lung cancer for FGFR4, MAP3K9, and PAK5 kinases." (PMID 24817905, 2014). "In conclusion, we believe there is currently little evidence to suggest that the Gly388Arg polymorphism of FGFR4 represents a robust marker of lung cancer prognosis." (PMID 17519899, 2007). "To evaluate the prognostic significance of the FGFR4 Gly388Arg polymorphism in lung cancer, we analysed a cohort of 619 lung cancer patients." (PMID 17519899, 2007). "However, the biological significance of FGFR4 mutations in lung cancer remain to be determined experimentally." (PMID 34068816, 2021). "Therefore, further well-designed studies with large sample sizes are needed to confirm the role of FGFR4 G388R polymorphisms in lung cancer in future." (PMID 33446698, 2021). "Furthermore, we report clinical evidence that this variant has a potential prognostic role in lung cancer patients with tumors that express high levels of FGFR4." (PMID 29402970, 2018). "FGFR4 p.Gly388Arg variant has been found to be correlated with development and disease prognosis of breast cancer, cervical cancer, hepatocellular carcinoma, thyroid cancer, gastric cancer, soft tissue tumors, lung cancer, colon cancer, prostate cancer, and head and neck tumors." (PMID 33456465, 2020). "However, the effects of FGFR4 SNPs on the risk of lung cancer seem to be controversial." (PMID 32781755, 2020). "In this study, the potential targets of Pinellia ternata highly overlap with lung cancer pathological genes, with FGFR4, CDK2, JAK2, KDR, PAK4, PTK2 and PDGFRA being the core." (PMID 42149884, 2026). "Fibroblast Growth Factor Receptor 4 (FGFR4) has garnered attention as a key oncogenic driver in multiple malignancies, including liver, breast, lung cancers and CRC38-40." (PMID 41210688, 2025).
lung carcinoma (continued). "Collectively, these findings demonstrated the enhanced antitumor efficacy in two subcutaneous lung cancer model by co-targeting FGFR4 and cyclin D1-CDK4/6 signaling." (PMID 35463335, 2022). "Kaplan–Meier Plotter online tool showed that the expression of FGFR4 was closely related to the prognosis of lung cancer patients (HR = 0.84 [0.71 − 0.99], log‐rank P = 0.034)." (PMID 33407583, 2021). "Enhanced STAT3 signaling induced by FGFR4 G388R was confirmed in vivo with the FGFR4Arg385 knock-in mice and transgenic mouse models for breast and lung cancers." (PMID 32393201, 2020). "For instance, like methylation of the KL promoter region, how epigenetic regulation of KLB expression in relation to FGF19/FGFR4 signaling during lung cancer progression remains an interesting question." (PMID 31695781, 2019). "Activating mutations in FGFR1 were found in glioblastoma, FGFR2 is often mutated in endometrial carcinomas and lung cancers, FGFR3 mutations are frequently found in bladder tumors and melanoma, whereas FGFR4 is mutated in endometrial and lung cancers." (PMID 30577533, 2018). "The FGFR4-388Arg variant has been reported to promote the activation of pathways related to cancer, such as the STAT3 signaling pathway in murine breast and lung cancer models." (PMID 29402970, 2018). "In our patient cohort that included patients with ADC, SCC and a few other histologic types of lung cancer, we found that the FGFR4-388Arg variant correlated with poor OS and PFS in patients with high FGFR4 mRNA expression." (PMID 29402970, 2018). "Considering the lower endogenous expression of FGFR1, FGFR3 and FGFR4 in human lung cancer cell line H441 and H358, we forced expression of full-length FGFR1, FGFR3 and FGFR4 in H441 cells." (PMID 27893433, 2016). "However, previous studies show activation of the EGFR pathway by FGFR4 in lung cancers and colon cancers." (PMID 33037736, 2020). "However, the potential anti-tumorigenic role of FGFR4-388Gly should be reproduced in additional lung cancer cell lines and further studied in order to be confirmed." (PMID 29402970, 2018). "Moreover, a study using FGFR4 rs351855-A/A-knockin transgenic mice to investigate lung cancer observed a marked decrease in the number of tumor-infiltrating CD8-positive T cells and a significant increase in regulatory T cell proportions compared with those from the G/G-knockin mice." (PMID 32781755, 2020). "While we employed a comprehensive set of statistical tests, including those sensitive to the detection of differences in early survival, our data provide little evidence to support the tenet that the FGFR4 Gly388Arg polymorphism is a clinically useful marker for lung cancer prognosis." (PMID 17519899, 2007). "In lung cancer, GLI Family Zinc Finger 2 (GLI2) acts as the downstream gene of FGF19/FGFR4, and GLI2 can directly transcriptionally upregulate FGF19 expression, forming the FGF19-GLI2-FGF19 feedback loop to promote metastasis." (PMID 36923538, 2023). "Several gatekeeper mutations in the FGFR family have been reported in preclinical studies in several cancer models, including FGFR1 V561M in lung cancer, FGFR2 V565I/N550K/V564F in endometrial cancer and cholangiocarcinoma, FGFR3 V555M in myeloma and FGFR4 V550L/V550E in rhabdomyosarcoma." (PMID 34068816, 2021). "In our present study using lung cancer cell lines, FGFR1 is most abundant receptor of the four family proteins in afatinib-resistant clones of PC9, and there was no enhancement in expression of other FGFR family proteins FGFR2, FGFR3 and FGFR4." (PMID 25115383, 2014). "Furthermore, our findings do not indicate that the FGFR4 genotype is an independent predictor of prognosis for lung cancer." (PMID 17519899, 2007). "It appeared that the FGF19/FGFR4 signaling could still function in lung cancer independent of KLB." (PMID 31695781, 2019).
cardiac hypertrophy (26 papers, 2016 to 2025). "To determine the potential role of FGF23/FGFR4 in pregnancy-associated cardiac hypertrophy, we conducted histological analyses of hearts from wild-type and FGFR4−/− mice." (PMID 39452290, 2024). "It has also been shown that myocardial FGF23/FGFR4 expression is associated with cardiac hypertrophy among patients with end-stage renal disease." (PMID 27400031, 2016). "Furthermore, the activation of FGFR4 by the introduction of a Fgfr4 gain-of-function mutation induces cardiac hypertrophy and the growth of individual myocytes in mice." (PMID 39452290, 2024). "FGF23 may mediate some of this risk by promoting cardiac hypertrophy via activation of fibroblast growth factor receptor 4 on cardiomyocytes." (PMID 34359914, 2021). "Our study shows for the first time that FGFR4 signaling plays an important role in the growth of cardiac myocytes during physiologic cardiac hypertrophy." (PMID 39452290, 2024). "Combined with previous studies, our analyses highlight the importance of FGFR4 signaling in all forms of cardiac hypertrophy." (PMID 39452290, 2024). "We have identified FGFR4 as a receptor tyrosine kinase that induces physiologic cardiac hypertrophy." (PMID 39452290, 2024). "To study FGF23/FGFR4 in a second model of physiologic cardiac hypertrophy, we analyzed Burmese pythons, which experience up to 40% increase in cardiac mass after ingesting a meal." (PMID 39452290, 2024). "Of note, the high FGF23 levels cause an increase in FGFR4 expression, showing that FGFR4 is responsible for the crucial role of FGF23 in cardiac hypertrophy." (PMID 36831276, 2023). "As shown here, inhibited FGFR4 signaling attenuated both cardiac hypertrophy and interstitial myocardial fibrosis in db/db mice." (PMID 35513431, 2022). "While short-term FGF21 elevation can be cardio-protective, we find that in type 2 diabetes (T2D) in mice, where serum FGF21 levels are elevated, FGFR4 activation induces concentric cardiac hypertrophy." (PMID 35513431, 2022). "It is important to underline that high FGF23 levels induce upregulation of FGFR4 expression, indicating the induction of cardiac hypertrophy via FGFR4." (PMID 34065339, 2021). "FGF23 has a direct impact on the heart that promotes ventricular hypertrophy acting via FGF receptor 4 (FGFR4) in cardiomyocytes." (PMID 34359914, 2021). "Although experimental data in mice indicated the relative expression of FGFR3 and FGFR1 in isolated adult ventricular cardiomyocytes is higher compared to FGFR4, the major functional significance in cardiac hypertrophy development seems to belong to FGFR4." (PMID 34065339, 2021). "As a potential mechanism of these observations, FGF23 is reported to induce cardiac hypertrophy via Klotho-independent signaling through the FGFR4." (PMID 34765890, 2021). "Circulating FGF23 as well as FGF23 secreted by cardiomyocytes interact with a specific receptor FGFR4 to induce myocardial hypertrophy and fibrosis." (PMID 33924991, 2021). "Recently, we analyzed myocardial autopsy samples of deceased patients with childhood-onset ESRD and investigated the well-established FGF23/FGFR4 signaling cascade mediating cardiac hypertrophy." (PMID 29892269, 2018). "In these patients, FGFR4 expression positively correlated with the size of individual cardiac myocytes suggesting a causative relationship between FGFR4/PLCγ/calcineurin/NFAT activation and the induction of cardiac hypertrophy in humans." (PMID 29770125, 2018). "FGF23 appears to be a novel circulating factor that induces cardiac hypertrophy via activating FGFR4 and subsequent calcineurin/NFAT signaling in cardiac myocytes." (PMID 28512310, 2017). "To obtain further insight into potential FGFR-mediated signalling mechanisms in TAC-induced cardiac hypertrophy, we investigated mRNA expression of Fgfr1, Fgfr3 and Fgfr4 in WT, VDRΔ/Δ, Fgf23−/−/VDRΔ/Δ, and Klotho−/−/VDRΔ/Δ mice, 4 weeks after TAC." (PMID 28900153, 2017).